ESRP2 (epithelial splicing regulatory protein 2)
Diseases named in the same sentence as ESRP2 in open-access papers (continued):
Sharing a sentence is not in itself a finding about the gene and the disease.
prostate tumours (3 papers, 2019 to 2023). "ESRP1 and ESRP2 are encoded by genes that are important within the epithelial cells from which prostate tumours are derived, and then play an important role in subsequent tumour development." (PMID 37752235, 2023). "Potential future therapies could be designed to target ESRP1 and ESRP2 protein activity or their regulated splice isoforms in aggressive prostate tumours." (PMID 37752235, 2023). "Since ESRP1 and ESRP2 are over-expressed in aggressive prostate tumours, could they also be targeted to reduce the growth of primary prostate tumours?" (PMID 37752235, 2023). "We also used these same samples to assess if the observed up-regulation of ESRP1 and ESRP2 could result from prostate tumours consisting of a more pure population of epithelial-derived cells compared to matched tissue." (PMID 31478829, 2019). "Hence, by expressing higher levels of ESRP1 and ESRP2, more aggressive primary prostate tumours may maintain an epithelial gene expression environment to result in a growth advantage." (PMID 37752235, 2023). "Notably, in line with the event identified in our study, exon 5 of RPS24, an ESRP2-repressed exon, is frequently skipped in prostate tumour tissue and correlates with hypoxia in PCa samples, suggesting its AS may serve as a tumour hypoxia marker." (PMID 37924098, 2023). "Thus, ESRP1 and ESRP2 expression could also be indirectly activated via androgen-regulation of the ERG transcription factor in prostate tumours containing the TMPRS22-ERG genetic fusion." (PMID 37752235, 2023). "ESRP1 and ESRP2 both activate splicing of NUMB exon 3, and splicing of this exon in prostate tumours correlates with a reduced time until biochemical tumour recurrence in patients." (PMID 37752235, 2023). "Immunohistochemistry of ~19,000 prostate tumours correlated high levels of ESRP1 and ESRP2 protein expression with more rapid biochemical tumour recurrence, higher Gleason scores, higher tumour stages and increased numbers of lymph node metastases." (PMID 37752235, 2023). "RNA-seq data from prostate tumours show that ADT reduces expression levels of both ESRP1 and ESRP2 genes." (PMID 37752235, 2023). "The fact that prostate tumours originate from epithelial cells that already express ESRP1 and ESRP2, and then the ESRP1 and ESRP2 genes subsequently become important within a disease context, fits with the definition of a specific group of oncogenes called lineage-survival oncogenes." (PMID 37752235, 2023). "Why might primary prostate tumours express high levels of ESRP1 and ESRP2 as a strategy to increase tumour growth?" (PMID 37752235, 2023). "What could be the selective advantage for more aggressive prostate tumours to express higher levels of ESRP1 and ESRP2?" (PMID 37752235, 2023). "ESRP2 and its paralog ESRP1 are highly expressed in primary prostate tumours." (PMID 31478829, 2019). "Similarly, MYO1B exon 23 (skipped in response to ESRP2) is both overall more skipped in prostate tumour versus normal, and more skipped in higher Gleason grade cancers." (PMID 31478829, 2019).
Wilms tumor (3 papers, 2022 to 2024). An embryonal neoplasm characterized by the presence of epithelial, mesenchymal, and blastema components. "We show that in Wilms tumour, ESRP2 is commonly inactivated by DNA methylation at an early stage of carcinogenesis." (PMID 34520622, 2022). "We found that ESRP1 and ESRP2 are over-expressed in hFK3 with respect to hFK1 (as well as the Wilms’ tumor xenografts WT37, WT14, and WT11)." (PMID 36380228, 2022). "Specifically in Wilms’ tumor, a recent study showed that the splicing regulator ESRP2 is repressed by DNA methylation, whereas the overexpression of ESRP2 in Wilms’ tumor cell lines promotes alternative splicing and inhibits cell proliferation both in vitro and in vivo." (PMID 38674106, 2024). "This might also explain the heterogeneity in expression levels of QKI, and also the fact that unlike ESRP1 and ESRP2, the expression levels of RBFOX2 in the Wilms’ tumor xenograft samples are heterogeneous and not similar to those in hFK1." (PMID 36380228, 2022).
breast tumors (2 papers, 2022 to 2025). "Analysis of ERα genome-binding profiles in cell lines and primary breast tumors showed its binding in the proximity of ESRP1 and ESRP2 genes, whose expression is strongly decreased by ERα silencing in hormone-deprived conditions." (PMID 35887187, 2022).
head and neck carcinoma (2 papers, 2017 to 2023). A carcinoma that arises from the head and neck region. "ESRP2 does not currently appear to be connected to the occurrence of neurological disorders, although its downregulation is connected to invasive head and neck cancer and oral squamous cell carcinogenesis (OSCC)." (PMID 37446229, 2023).
hepatocellular carcinoma (2 papers, 2021 to 2024). A malignant tumor that arises from hepatocytes. "Three splicing factors, CELF2, ESRP2 (epithelial splicing regulatory protein 2), and SRSF5 (serine- and arginine-rich splicing factor 5), which are substantially downregulated in hepatocellular carcinoma samples, were found to be responsible for splicing dysregulation in hepatocellular carcinoma." (PMID 34681716, 2021).
lymph node metastasis (2 papers, 2020 to 2024). "Both, high ESRP1 and high ESRP2 staining were significantly associated with adverse tumor features, including advanced tumor stage, high Gleason grade, presence of lymph node metastasis (p < 0.0001 each), and high early PSA recurrence (p < 0.0001 each)." (PMID 33339518, 2020).
orofacial cleft (2 papers, 2020 to 2025). A disorder of facial skeleton that is characterized by cleft lip and/or cleft palate that result in feeding, speech and hearing problems caused by failures during development. "ESRP2 genetic variants in humans are associated with orofacial clefts, and Esrp1 and Esrp1/2 knockout mice display a bilateral cleft of the lip, primary and secondary palate." (PMID 33234718, 2020). "To assay whether ESRP2, which has been previously reported to be associated with orofacial clefts, is also associated with congenital hypopituitarism, we analyzed clinical and genomic data in the Arcus database from the Children's Hospital of Philadelphia." (PMID 41111330, 2025). "Therefore, the ESRP2 variant remains the most likely pathogenic variant in this individual that explains both pituitary abnormality and orofacial cleft." (PMID 41111330, 2025). "Gene variant in ESRP2 was also recently reported in human orofacial cleft cohorts." (PMID 33234718, 2020).
benign prostate hyperplasia (1 paper, 2019). "(A) Real-time PCR analysis of ESRP1 and ESRP2 mRNA from patients with benign prostate hyperplasia (BPH) and 17 malignant samples from transurothelial resection of the prostate (TURP) samples." (PMID 31478829, 2019).
cholangiocarcinoma (1 paper, 2024). A carcinoma that arises from the intrahepatic biliary tree (intrahepatic cholangiocarcinoma) or from the junction, or adjacent to the junction, of the right and left hepatic ducts (hilar cholangiocarcinoma). "In chronic inflammation progression, ESRP2 expression is inhibited, and inactive NF2 causes downstream YAP/TAZ activity to increase and promotes cholangiocarcinoma in chronic liver injury." (PMID 38302461, 2024). "ESRP2 plays an important role in the progression of NAFLD to cholangiocarcinoma." (PMID 38302461, 2024).
clear cell sarcoma (1 paper, 2022). A rare malignant neoplasm with melanocytic differentiation characterized by the presence of polygonal or spindle shaped clear cells. "In data sets GSE73187 and GSE4487, ESRP2 was also found to be hypermethylated in clear cell sarcomas and rhabdoid tumours." (PMID 34520622, 2022).
clear cell sarcomas of the kidney (1 paper, 2022). "ESRP2 DNA hypermethylation was also observed in 10 of 16 (63%) non‐WT childhood renal tumours, especially in clear cell sarcomas of the kidney and in rhabdoid tumours." (PMID 34520622, 2022).
cleft lip (1 paper, 2025). Congenital defect in the upper lip where the maxillary prominence fails to merge with the merged medial nasal prominences. "In the mouse, ablation of Esrp1 causes a bilateral cleft lip and cleft palate, and ablation of both Esrp1 and Esrp2 leads to a more severe bilateral cleft lip and palate phenotype." (PMID 41111330, 2025). "Finally, ESRP2 human gene variants have been found in cleft lip and palate clinical cohorts, whereas, so far, ESRP1 gene variants have been associated with hearing deficits." (PMID 41111330, 2025).
hypopituitarism (1 paper, 2025). A condition of diminution or cessation of secretion of one or more hormones from the anterior pituitary gland. "Further, we describe an individual with cleft palate and hypopituitarism who harbors a nucleotide variant in the RNA-binding domain of ESRP2." (PMID 41111330, 2025).
liver disease (1 paper, 2021). "Altered ESRP2 expression has also been found in human HCC samples, so it is reasonable to expect that ESRP2-mediated splicing plays a role in liver disease as inflammation is a marker of progression from NAFLD to NASH." (PMID 33716968, 2021).
oral cancer (1 paper, 2020). "However, it remains to be elucidated how ESRP2 is able to represses ZEB1/2 expression and whether splicing-independent mechanisms, e.g., regulation of miRNA biogenesis might underlie ESRP2 function in oral cancer cells." (PMID 32957697, 2020). "Moreover, the authors identified distinct mechanisms of action of ESRP1 and ESRP2 in oral cancer cells." (PMID 32957697, 2020).
pituitary adenomas (1 paper, 2021). "Increased expression of IFNG-AS1 could facilitate HP75 cell proliferation, cell invasion, migration, and suppressed cell apoptosis in pituitary adenomas by regulating epithelial splicing regulatory protein 2 (ESRP2)." (PMID 34872454, 2021).
prostate adenocarcinoma (1 paper, 2019). "High ESRP2 expression was not prognostic of disease progression in the TCGA (PRostate ADenocarcinoma) PRAD cohort analysed using KM-express, but high expression of ESRP1 associated with a significantly reduced time to first biochemical recurrence (p=0.022)." (PMID 31478829, 2019).
renal aplasia (1 paper, 2016). "Ablation of Esrp1 in mice, alone or together with its paralog Esrp2, was associated with reduced kidney size and increased incidence of renal aplasia." (PMID 27404344, 2016).
tumor (27 papers, 2016 to 2025). "The analysis of AS changes indicates that ESRP1 and ESRP2 control the expression of exons that are associated with specific tumor molecular features and patient clinical outcomes." (PMID 35887187, 2022). "RPS24 exon 5 (repressed by ESRP2, and overall more skipped in tumours) is skipped more in larger more advanced tumours, making the mRNA isoform associated with a decreased time to biochemical recurrence." (PMID 31478829, 2019). "In contrast, our data showed that high ESRP1 as well as ESRP2 in tumor tissue are associated with favorable overall survival outcome." (PMID 27650542, 2016). "Consistently, HCC specimens with ESRP2 silencing showed higher methylation density compared to non‐tumor tissues, supporting that promoter hypermethylation might be the major cause of ESRP2 downregulation in HCC." (PMID 37985644, 2024). "Additionally, to examine whether TAK1 variants could rescue the tumor‐suppressive function of ESRP2, we introduced both variants into ESRP2‐overexpresed HCC cells." (PMID 37985644, 2024). "The protein expression level of ESRP2 was also determined by IHC staining in paired clinical samples, and a relatively strong ESRP2 expression was observed in non‐tumor liver tissues." (PMID 37985644, 2024). "Conversely, silencing of ESRP2 led to an elevated tumorigenesis ratio and increased tumor weights relative to the control group." (PMID 37985644, 2024). "We further verified that ESRP2 inhibited tumor cell proliferation and migration by suppressing the splicing of the oncofetal variant of TAK1 transcripts and inactivating p38MAPK signaling." (PMID 37985644, 2024). "ESRP2 expression was downregulated in tumor tissues compared with non‐tumor counterparts and decreased in middle/late‐stage and poorly differentiated tumors compared with early stage and well‐differentiated ones, respectively." (PMID 37985644, 2024). "Epithelial splicing regulatory proteins 1 and 2 (ESRP1 and ESRP2) manipulate tumor epithelial-to-mesenchymal transition (EMT)." (PMID 36803157, 2023). "In vitro, altered levels of ESRP1 or ESRP2 caused a switch of FGFR2 splicing between FGFR2-IIIb and FGFR2-IIIc, resulting in changes in tumor cell growth and metastatic potential." (PMID 37090731, 2023). "In vivo, increased ESRP1 or ESRP2 levels in BC cells not only inhibited the growth of the xenografted tumor formation in nude mice, but also reduced the occurrence of lung metastasis, partially through altering polarization of tumor-associated macrophages." (PMID 37090731, 2023). "Here we discuss how expression of the splicing regulators ESRP1 and ESRP2, and how their role as “masterminds” of epithelial splicing patterns, have been identified as markers of aggressively proliferating prostate primary tumours." (PMID 37752235, 2023). "In vitro, altered ESRP1 or ESRP2 levels caused a switch of alternative splicing of FGFR2 between FGFR2-IIIb and FGFR2-IIIc, resulting in changes in tumor cell growth and metastatic potential." (PMID 37090731, 2023). "In vivo, re-expression of ESRP1 or ESRP2 in BC cells not only inhibited the growth of the xenografted tumor formation in nude mice, but also reduced the occurrence of lung metastasis, partially through altering polarization of tumor-associated macrophages." (PMID 37090731, 2023). "Most importantly, the re-expression of ESRP1 and ESRP2 in the invasive T24 BC cells significantly decreased the presence of circulating tumor cells and the occurrence of the lung metastasis." (PMID 37090731, 2023). "Studies have revealed the clinical significance of ESRP1 and ESRP2 in tumor progression and metastasis." (PMID 35887187, 2022). "Western blotting of excised tumours demonstrated that doxycycline treatment had induced high‐level ESRP2 expression in all E200L tumours, with the notable exception of 1E‐L (where the tumour grew larger) and V200‐induced tumours." (PMID 34520622, 2022).
tumor (continued). "When ESRP2 was overexpressed in WT cell lines, it inhibited cellular proliferation in vitro, and in vivo it suppressed tumour growth of orthotopic xenografts in nude mice." (PMID 34520622, 2022). "ESRP2 inhibited cellular proliferation in vitro, and in vivo it suppressed tumour growth of orthotopic xenografts in nude mice, demonstrating that ESRP2 acts as a tumour suppressor gene in WT." (PMID 34520622, 2022). "We show that ESRP2 is frequently silenced by DNA hypermethylation in WT and that it acts as a tumour suppressor gene, regulating alternative splicing in novel genes, some of which affect pathways known to be important in kidney development." (PMID 34520622, 2022). "This therefore demonstrated a strong correlation between ESRP2 expression and suppression of tumour growth." (PMID 34520622, 2022). "Another splicing regulator gene, ESRP2, was also predicted to present methylation diversity in tumor cells." (PMID 32528944, 2020). "In our TMA analyses, 12,140 (68.4%) were interpretable for ESRP1 and 12,962 (73.0%) for ESRP2 (out of a total of 17,747 tumor samples)." (PMID 33339518, 2020). "FLNB exon 31 (activated by ESRP2) actually shows slightly reduced splicing inclusion in larger, more aggressive tumours." (PMID 31478829, 2019). "Epithelial splicing regulatory protein 2 (ESRP2), downregulated in cadmium clones, is an epithelial mRNA splicing factor necessary for normal mRNA processing that functions as a tumor suppressor." (PMID 27186882, 2016). "Notably, tumors induced by ESRP2‐transfected cells showed smaller volumes and decreased tumor weights compared to tumors induced by vector‐transfected cells." (PMID 37985644, 2024). "Moreover, NOVA1 and ESRP2 expression were statistically increased in OSCC with an expansive front of tumor invasion compared to OSCC with an infiltrative front of tumor invasion (p = 0.04 and 0.06, respectively)." (PMID 39000035, 2024). "Similarly, our results showed that NOVA1 and ESRP2 were overexpressed in OSCC with uniform tumor invasion edges compared to poorly defined ones (p = 0.04 and 0.06, respectively)." (PMID 39000035, 2024). "Modulating expression of ESRP1 and ESRP2 in aggressive tumours could inhibit cell proliferation, but also have unintended side effects." (PMID 37752235, 2023). "Significantly smaller tumors were observed in mice grafted with either ESRP1 or ESRP2, compared to scrambled-grafted mice, while the reduction in tumor was even more pronounced in mice grafted with T24 cells transfected with combined ESRP1/2, shown by quantification, and by representative images." (PMID 37090731, 2023). "Could ESRP1 and ESRP2 also operate as lineage-survival oncogenes during the development of other tumours, many of which also develop from epithelial tissues?" (PMID 37752235, 2023). "However, there is also data indicating that high levels of ESRP1 and ESRP2 gene expression more generally contribute to aggressive prostate primary tumour development and correlate with poorer patient prognosis." (PMID 37752235, 2023). "Coupled with our xenograft experiments that identify ESRP2 as a bona fide tumour suppressor gene, these results suggest that the tumour suppressor activity of ESRP2 in WT cell lines occurs mainly by altering cell growth properties, rather than by affecting cellular differentiation." (PMID 34520622, 2022). "They proposed that the Arkadia–ESRP2 axis could act as a tumor suppressor in ccRCC." (PMID 38893126, 2024). "Could ESRP1 and ESRP2 be lineage survival oncogenes in other kinds of tumour?" (PMID 37752235, 2023). "Hence re-expression of ESRP1 and ESRP2 proteins could in principle be part of a gene expression programme enabling successful metastatic growth once secondary tumours have seeded." (PMID 37752235, 2023).